CD4 (CD4 molecule)
Diseases named in the same sentence as CD4 in open-access papers (continued):
Sharing a sentence is not in itself a finding about the gene and the disease.
tumor (continued). "This was conceived decades ago following the identification of a wealth of CD8+ and CD4+ epitopes in several tumor antigens, mainly in studies of melanoma." (PMID 24212974, 2011). "From immunohistochemical assay, human CD4+ and CD8+ T cells infiltrated in tumor were closely associated with antitumor effects and tumor apoptosis." (PMID 21649881, 2011). "Anti 4-1BB treatment, with or without CTLA-4 blockade, induced approximately 75% of CD8+ and 45% of CD4+ effector T-cells in the tumor to express the killer cell lectin-like receptor G1 (KLRG1)." (PMID 21559358, 2011). "aAPC-expanded TILs undergo numerical expansion of tumor antigen-specific cells, remain amenable to secondary aAPC-based expansion, and have low CD4/CD8 ratios and FOXP3+ CD4+ cell frequencies." (PMID 21827675, 2011). "Peptides STEAP281-296 and EZH295-109 are newly described CD4 T-cell epitopes that can elicit effective anti-tumor T-cell responses against STEAP or EZH2 expressing LC cell lines." (PMID 22053850, 2011). "In another study, myeloma tumors were infiltrated by macrophages within 3 days, followed by tumor-specific CD4+ Th1 cells at day 6 after which the macrophages started to kill tumor cells." (PMID 22176642, 2011). "Expansion of CD4+CD25high Treg cells within the tumor microenvironment and peripheral blood has so far been accepted as a hallmark of cancer." (PMID 21904560, 2011). "The mechanisms underlying the suppressive effects of Tregs include inhibiting the activity of a variety of immune cells that are tumor specific such as CD4 and CD8 cells, B cells, NK cells, natural killer T cells (NKT), and DCs." (PMID 22046558, 2011). "IL-4 is produced by tumor-infiltrating CD4 T cells and there is mounting evidence of its relevance in the polarization of macrophages with pro-tumor functions." (PMID 24213109, 2011). "Long-term culture of tumor-derived T cells in high-dose interleukin-2 (IL-2) allows for the generation of high numbers of TILs (>1 × 1011) but with preferential expansion of CD4+ lymphocytes." (PMID 21827675, 2011). "In contrast to the CD8 compartment, only CTLA-4 blockade appeared capable of driving CD4+ effector T-cell proliferation within the tumor." (PMID 21559358, 2011). "For example, a recent study showed that DCs cultured under low oxygen resulted in skewing from a type 1 helper CD4+ T cell phenotype to a type 2 helper CD4+ T cell phenotype, which is more immunosuppressive and less beneficial for tumor killing." (PMID 22190938, 2011). "Each individual contained a small number of large (high frequency) tumor clones alongside some smaller (lower frequency) clones in the CD4+ T cell population." (PMID 21573129, 2011). "In tumor immunity, Treg have primarily been described for their ability to impair the function of tumor-specific CD4+ and CD8+ T cells." (PMID 22110524, 2011). "These profiles were mirrored by the spectratypes of the CD4+ cell populations in all four tumor samples (middle column)." (PMID 21573129, 2011). "Several experiments indicated that the anti-angiogenic and anti-tumor activity in mice immunized with xenogeneic endothelial cells was achieved by induction of CD4+ T lymphocyte-dependent endothelial cell-specific antibodies." (PMID 21385454, 2011). "Autologous T cells stimulated with these fusions were predominantly CD4+, activated, and reacted specifically against the fusion clones and also against the tumor cell fusion partner." (PMID 21943054, 2011). "All in all, IFN-γ is correlated with several direct and indirect antitumor properties and tumor responsiveness to IFN-γ is necessary for IFN-γ-dependent inhibition of tumor angiogenesis by CD4+ T cells." (PMID 21943203, 2011). "Specifically, the sequence data for Vβ1 in CD4+ cells from Bird 11 identifies three large tumor-like clones, “LDGTGGY” (liver only), “RRLTGD” (kidney and as a singlet in ovary) and “LDTGGS” (liver, kidney and ovary)." (PMID 21573129, 2011).
tumor (continued). "Growing body of evidence indicates that tumor-specific CD4+ T cells and there subtypes (Th1, Th2, Treg or Th17) are directly involved in mediating in vivo tumor regression or evasion, as well as CD8+ T cells." (PMID 21943203, 2011). "The improved anti-tumor immune response was accompanied by a transient decrease in the frequency and absolute number of CD4+CD25+FoxP3+ T cells (Tregs)." (PMID 21859450, 2011). "In conclusion, immunization of BALB/c mice with PSA-MPyVLPs, loaded onto DCs and co-injected with CpG, induces an efficient PSA-specific tumor protective immune response, including both CD4+ and CD8+ cells with a low induction of anti-VLP antibodies." (PMID 21858228, 2011). "The distinction between the Vav-SB and CD4-SB tumor models is clearer when the genomic distributions of driver mutations are compared." (PMID 21931803, 2011). "Phenotypic characterization of TICs revealed that α-TEA caused a significant increase (P = 0.0481) in the frequency of activated CD4+ T cells in the tumor microenvironment on day 18 post-tumor injection." (PMID 21232138, 2011). "In the absence of culturable T-cell lines generated from these tumors, we tentatively defined tumor-like clones as CD4-enriched and representing greater than 30% of the sequences in any one site (most were much higher frequency than 30%)." (PMID 21573129, 2011). "Our data indicated that anti-CD4 treatment on days 4 and 10 of primary tumor growth only transiently eliminated CD4+ T cells, with help returning as early as 10 days post-treatment." (PMID 22046294, 2011). "Early animal studies using vaccination strategies against EGFRvIII reported increased numbers of tumor-infiltrating CD4+, CD8+, natural killer (NK) cells, and macrophages as well as a dramatic increase in survival." (PMID 22190972, 2011). "Taken together these results, we believe that the simultaneous induction of STEAP- and EZH2-specific CD4 and CD8 T-cell responses would be more effective in achieving anti-tumor effects than the separate induction of CD4, or CD8 T-cell responses." (PMID 22053850, 2011). "That the α-TEA-mediated antitumor effect had a T cell-dependent component was demonstrated by the partial abrogation of tumor suppression when CD4+ and CD8+ T cells were depleted." (PMID 21232138, 2011). "Because our treatment model involves B16 tumor removal when CD4 T cells are completely depleted, CD4 T cell repopulation was assessed in tumor-free mice." (PMID 22046294, 2011). "In order to reprogram macrophages directly in the tumor-microenvironment, it is essential that CD4+ Th1 cells are locally present." (PMID 22176642, 2011). "TCRα chains were amplified from naive CD44−CD62L+Foxp3GFP-, activated/memory CD44+CD62L−Foxp3GFP- and Foxp3GFPlo and Foxp3GFPhi Treg CD4+ cells sorted from control and draining lymph nodes and tumor infiltrate." (PMID 21049016, 2010). "DTA-1 led to a significant decrease in intra-tumor Treg frequency as a percentage of CD4+ TILs (40% of CD4+ TIL for IgG, compared with 18% for DTA-1, p = 0.02)." (PMID 20454651, 2010). "How CD4+ T cells mediate anti-tumor immunity is still under investigation, but it appears that the underlying mechanisms are multiple." (PMID 21152437, 2010). "Machetti and colleagues (2006) reported similar results and believe that a greater percentage of CD4+ T-cells is correlated with the induction of angiogenesis, secretion of immuno-inhibitory cytokines and intra-tumor estrogen conversion." (PMID 20525350, 2010). "An EBNA1-specific CD4+ T-cell response was found to be required and sufficient to suppress tumor growth in a mouse model." (PMID 20953370, 2010). "Ep63K-specific CD4+ T cells undergo efficient clonal expansion in response to antigen produced by tumor cells." (PMID 21049016, 2010). "Some CD4+ T cells can kill tumor cells either via Fas Ligand-dependent or perforin-dependent pathways." (PMID 21437175, 2010).
tumor (continued). "CTLs are the major killers of tumor cells; they accomplish the killing with the help of CD4+ T cells, which can induce potential long-term CD8+ T-cell responses by producing various cytokines." (PMID 21197274, 2010). "Because the total number of cells was also increased two-fold in the lymph nodes of tumor-treated animals, the total increase in CD4+ CD25+ Foxp3+ was approximately four-fold, compared to the PBS-injected animals." (PMID 21170379, 2010). "Increasing evidence suggests that the induction of optimal antitumor immunity requires both CD4+ and CD8+ T cells specific for tumor-associated Ags." (PMID 20953370, 2010). "To model the native ascites tumor environment as closely as possible in vitro, we analyzed bulk ascites cell pellets, which in addition to CD8+ and CD4+ T cells, contained resident tumor cells, Tregs, B cells, NK cells, and CD14+ cells." (PMID 21203522, 2010). "Of the 20 most abundant clones in the population of naive CD4+ T cells in control lymph nodes of tumor-bearing mice, 16 were also most abundant in naive cells of unmanipulated mice." (PMID 21049016, 2010). "Under normal conditions, APCs that scavenge tumor cell debris and migrate to lymphoid tissues can interact with CD4+ and CD8+ T-cells to induce activation of T-cells capable of recognizing tumor-specific or tumor-associated antigens." (PMID 21127709, 2010). "In a similar way, CD4+ T cells can also contribute to tumor destruction or facilitate its development." (PMID 21437225, 2010). "Treg cells have been shown to negatively affect tumor immunity as the depletion of CD4+CD25+FoxP3+ Treg from tumor tissue and the TSLN has been shown to facilitate tumor rejection." (PMID 20946663, 2010). "We performed immunohistology on the tumor graft site, and sections were incubated with anti-CD4, anti-CD25, anti-FoxP3, and anti-GITR antibodies." (PMID 21170379, 2010). "The CD4+ cells' probable mechanism of action involves the release of cytokines and other mediators, which either targets the tumor directly or the tumor's vasculature." (PMID 21437175, 2010). "In this study, the role of CD8+, CD4+ and NK cells in tumour rejection was examined after Her2MPtVLP immunization." (PMID 20657846, 2010). "The use of CD8 co-receptor independent tumor-specific TCRs would permit to exploit both CD4+ and CD8+ T-specific effector functions." (PMID 20711505, 2010). "Using this strategy we observed that recombinant Ad5 induced strong CD4+ T cell responses against the heterologous tumor antigens." (PMID 21152437, 2010). "Further analysis demonstrated that animals with tumor infiltrating lymphocytes composition with higher relative percentage of CD4+ T-cells and lower proportion of CD8+ T-cells had lower, but not significant (P = 0.191) survival rate (Figure." (PMID 20525350, 2010). "Since CD4+ regulatory T cells have been shown previously to play a role in tumor progression in this system, we only used anti-CD8 to investigate a role for CD8+ T cells." (PMID 20426873, 2010). "Recent study suggested that Th17 cells, a distinct subset of CD4+ T cells, infiltrated in tumor mass and played a controversial role in tumor immunity." (PMID 20981279, 2010). "This was accompanied by a modest increase in the total intra-tumor CD8:CD4 T-cell ratio (0.7 for IgG compared with 1.3 for DTA-1-treated mice, p = 0.04)." (PMID 20454651, 2010). "Of the two tumor-specific T lymphocyte subsets, CD8+ T cells recognize tumor antigen-derived peptides in the context of MHC class I molecules whereas CD4+ T cells respond to peptide-MHC class II complexes." (PMID 21152437, 2010). "Expression of MHC class I and II molecules, costimulatory molecules (CD80 and CD86), and adhesion molecules (ICAM-1 and LFA-3) on tumor/DC fusions is essential for antigen processing, presentation, and subsequent activation of both CD4+ and CD8+ T cells." (PMID 21048993, 2010).
tumor (continued). "This obvious importance of CD4+ T cells in tumor control has strongly stimulated the interest in epitopes recognized by CD4+ T cells." (PMID 21152437, 2010). "It has also been reported that human CD4+ regulatory NKT cells can suppress the expansion of tumor antigen-specific CTLs via Th2 cytokines such as IL-4 and IL-10." (PMID 20052413, 2010). "On the contrary, there are other studies with DNA vaccines, where elimination of CD4+ cells abolishes tumour protection in the effector phase." (PMID 20657846, 2010). "These clones constitute 41.0, 6.7 and 12.6% of activated CD4+ T cells and 29.9, 4.7 and 0% of Treg cells in tumors, tumor draining lymph nodes and control lymph nodes respectively." (PMID 21049016, 2010). "Changes in tumor growth, cell cytotoxic activity and populations of CD4+/FoxP3+ T regulatory cells (Treg) in the TSLN were evaluated." (PMID 20946663, 2010). "Several studies have shown that CD4+ T regulatory cells (Tregs) promote tumor progression by inhibiting the functions of T cells and natural killer (NK) cells and that their accumulation is associated with a worse prognosis." (PMID 21437225, 2010). "Mice undergoing dendritic cell therapy had more CD4+ T cells in tumor-draining lymph nodes and tumors and a higher fraction of CD4+ T cells expressed an activated phenotype what shows that dendritic cells were effectively stimulating Ep63K-specific T cells." (PMID 21049016, 2010). "In fact, evidence is accumulating that CD4+ T cells can actually induce strong anti-tumor immune responses, as recently demonstrated in mice and humans." (PMID 21152437, 2010). "In consideration of the critical role that CD4+ T cells play in inducing the SHR process, our data suggest a novel role for CD4+ T cells in the tumor suppression of GC/post-GC B cells." (PMID 21179576, 2010). "CD4+Foxp3GFP+ cells in the tumor draining lymph nodes and tumors express higher levels of CTLA-4 and GITR than activated Foxp3GFP- cells." (PMID 21049016, 2010). "The direct co-stimulation of tumor-specific effector CD4+ and CD8+ T cells (Teffs) has been demonstrated, particularly in combination with active vaccination; yet, the in vivo effects of DTA-1 on Tregs have not been well-defined." (PMID 20454651, 2010). "Among the four subpopulations of naïve CD4+ T cells, type 1 CD4+ T cells (Th1) facilitate tumor rejection by assisting in the function of cytotoxic CD8+ T cells whereas type 2 CD4+ T cells (Th2) promote antibody production by B cells by secreting cytokines." (PMID 21437225, 2010). "The tumor cells typically have the phenotype of immature T-cells (CD4-/CD8- or CD4+/CD8+) although some tumors show a more mature surface phenotype (CD4+/CD8-or CD4-/CD8+)." (PMID 20132553, 2010). "We have established that Treg cells expressing TCRs shared with effector CD4+ T cells constitute about half of all Treg cells in the tumor site while in unmanipulated mice they account for only 10-15% of all Treg cells." (PMID 21049016, 2010). "The number of CD4+ cells (results were average of three view fields) was 7 in control tumor and 44 in ECDα2 boosted mice (P < 0.05)." (PMID 21067607, 2010). "In tumor-bearing mice treated with CD4-depleted DLN, 4T1 tumors regressed completely in 5/6 mice, with a growth curve that was little different from AIT with untreated or C'-treated cells." (PMID 21050466, 2010). "The role of CD4+ T cells in anti-tumor immunity has long been restricted to their helper function in primary activation and maintenance of antigen-specific cytotoxic CD8+ T cell responses." (PMID 21152437, 2010). "Tregs are a suppressive CD4+ T cell population that is present, along with primed effector T cells, in tumor and tumor-draining lymph nodes." (PMID 20712892, 2010). "CD4 is also a very well known inhibitor of tumour angiogenesis, thus supporting a link between the two pathways." (PMID 20426824, 2010).
tumor (continued). "No other variables, including age, BMI, Karnofsky score, baseline CD4 count, tumor stage, lesion location, number of lesions, or presence of edema were found to be associated with likelihood of improvement in multivariate analysis." (PMID 21103057, 2010). "T cells likely mediated the inhibitory effect, which was suggested by the significant infiltration of CD8+ and CD4+ T cells in fusion protein-treated tumour tissues." (PMID 21176167, 2010). "In order to determine which components of the immune system contribute to the anti-tumor effect induced by the vaccine, we depleted effector T cells (both CD4+ and CD8+), NK and NKT cells with depleting antibodies in vivo, after vaccination." (PMID 20844763, 2010). "Later a three-component GLP vaccine by Boons and coworkers (a three palmitic acid Pam3-CysSK4 moiety, a CD4+ and a B-Cell epitope) showed induction of strong tumor-specific IgG responses." (PMID 20574522, 2010). "When wild type CD4+ T cells were stimulated with anti-CD3 mAb in vitro for 24 hours, the CD4+ T cells from tumor-bearing mice produced lower levels of IFN-γ when compared with ones from non-tumor bearing wild type mice." (PMID 20167088, 2010). "In fact, the higher infiltration of CD4+ T-cells was observed in the groups with the worst prognosis [MC-BMT(+) and MC(+)], and was associated with tumor progression, metastasis and poor survival." (PMID 20525350, 2010). "It is also unlikely that tumour inhibition after depletion was due to low numbers of remaining CD4+ or CD8+ specific T-cells, since depletion was >97% initially for both subsets, and 70–80% three weeks after the last mAb injection." (PMID 20657846, 2010). "Adoptively transferred tumor antigen-specific CD4+ T cells have been demonstrated to mediate dormancy or regression of tumors, even eradication of large established tumor masses was observed." (PMID 21152437, 2010). "CD4 infiltrate was seen in all tumor bearing mice, with greater percentages of CD4 infiltrate seen in AIT + CYP treated tumors, as compared to untreated or CYP treated hosts (data not shown)." (PMID 21050466, 2010). "The TCR diversity of naive and activated CD4+ T cells increased in tumor draining lymph nodes in comparison to control lymph nodes and decreased in tumor tissue." (PMID 21049016, 2010). "CD4+ T cell response for anti-tumor immunity can be divided into different types depending upon their cytokine profile." (PMID 20205946, 2010). "In mice injected with tumor cells in TBHsp70 solution, staining for CD4, CD25, FoxP3 and GITR was observed in overlapping areas, mostly surrounding the tumor mass, as well as inside the tumor." (PMID 21170379, 2010). "In contrast, CD4+ T cell depletion completely abrogated the effects of DTA-1 on tumor growth, but also on activation of CD8+ T cells and NK cells." (PMID 20936139, 2010). "It is well accepted that tumor-specific CD4+ T cells essentially sustain the anti-tumor activity of CTL by licensing dendritic cells (DC) to effectively prime CTL or by maintaining profound CTL memory, as well as by direct stimulation of CTL." (PMID 21152437, 2010). "This excludes the possibility that some other class II MHC associated peptides could be recognized by CD4+ T cells and result in Treg induction and ensures that both effector and Treg cells are stimulated against the same antigenic peptide produced solely by tumor cells." (PMID 21049016, 2010). "Using multicolor confocal microscopy, the study also found a substantial accumulation of CD4+CD25+CD3+ T cells within the tumor mass among 104 tumor specimens from untreated EOC patients." (PMID 20146807, 2010). "The important role of CD4+CD25+ Tregs in controlling tumor growth was further highlighted by the demonstration that depletion of Tregs using anti-CD25 antibodies evokes effective antitumor immunity in mice." (PMID 21253521, 2010).